HSP90B1 (heat shock protein 90 beta family member 1)
Description:
ATP-dependent chaperone involved in the processing of proteins in the endoplasmic reticulum, regulating their transport. Together with MESD, acts as a modulator of the Wnt pathway by promoting the folding of LRP6, a coreceptor of the canonical Wnt pathway. When associated with CNPY3, required for proper folding of Toll-like receptors. Promotes folding and trafficking of TLR4 to the cell surface. May participate in the unfolding of cytosolic leaderless cargos (lacking the secretion signal sequence) such as the interleukin 1/IL-1 to facilitate their translocation into the ERGIC (endoplasmic reticulum-Golgi intermediate compartment) and secretion; the translocation process is mediated by the cargo receptor TMED10.
Synonyms: GRP94; TRA1; GP96; ECGP; HEL-S-125m; HEL35
Tractability: Small molecule: a structure with a bound ligand is known; a high-quality ligand is known; it belongs to a druggable protein family. Antibody: its Gene Ontology location is reachable by antibodies, with high confidence; UniProt predicts a signal peptide or a membrane-spanning region. PROTAC: ubiquitination databases record sites on it; its protein half-life has been measured; a small molecule that binds it is known.
Target class: Other membrane protein
Chemical probes: CHEMBL3426787, PU-WS13
Gene: Protein-coding gene on chromosome 12 (103,930,107 to 103,953,931, forward strand). Ensembl gene ENSG00000166598.
Subcellular location: Endoplasmic reticulum lumen; Sarcoplasmic reticulum lumen; Melanosome
Subcellular location (Human Protein Atlas): Endoplasmic reticulum
Pathways (Reactome):
Immune System: Interleukin-4 and Interleukin-13 signaling; Trafficking and processing of endosomal TLR
Metabolism of proteins: Post-translational protein phosphorylation; Regulation of Insulin-like Growth Factor (IGF) transport and uptake by Insulin-like Growth Factor Binding Proteins (IGFBPs)
Cellular responses to stimuli: ATF6 (ATF6-alpha) activates chaperone genes
Vesicle-mediated transport: Scavenging by Class A Receptors
Gene Ontology:
Molecular function: ATP-dependent protein folding chaperone; low-density lipoprotein particle receptor binding; protein binding; protein folding chaperone; protein phosphatase binding; protein phosphatase inhibitor activity; RNA binding; ATP binding; ATP hydrolysis activity; calcium ion binding; AP-3 adaptor complex binding
Biological process: actin rod assembly; cellular response to ATP; ERAD pathway; negative regulation of apoptotic process; positive regulation of toll-like receptor signaling pathway; positive regulation of Wnt signaling pathway; protein folding; protein localization to plasma membrane; response to hypoxia; retrograde protein transport, ER to cytosol; protein folding in endoplasmic reticulum; protein transport; response to endoplasmic reticulum stress; cellular response to manganese ion; response to hormone
Cellular component: cytosol; endoplasmic reticulum; endoplasmic reticulum lumen; endoplasmic reticulum membrane; extracellular exosome; focal adhesion; melanosome; membrane; midbody; nucleus; perinuclear region of cytoplasm; protein-containing complex; endocytic vesicle lumen; extracellular region; sarcoplasmic reticulum lumen; endoplasmic reticulum chaperone complex; plasma membrane; smooth endoplasmic reticulum
Genetic constraint (gnomAD): Loss-of-function variants: 14 observed, 67.12 expected, observed/expected ratio (o/e) 0.21, 90% interval 0.14 to 0.33. The upper end of that interval is the gene's LOEUF score, 0.33, which puts it in group 1 of 6, group 1 being the genes least tolerant of losing a copy. Missense variants: 489 observed, 760.14 expected, observed/expected ratio (o/e) 0.64, 90% interval 0.6 to 0.69. Synonymous variants: 225 observed, 266.46 expected, observed/expected ratio (o/e) 0.84, 90% interval 0.76 to 0.94.
Homologues: Orthologues: macaque HSP90B1 (99% identical), chimpanzee HSP90B1 (99% identical), pig HSP90B1 (98% identical), rabbit HSP90B1 (98% identical), dog HSP90B1 (97% identical), mouse Hsp90b1 (97% identical), rat Hsp90b1 (96% identical), guinea pig HSP90B1 (96% identical), tropical clawed frog hsp90b1 (86% identical), zebrafish hsp90b1 (84% identical), Caenorhabditis elegans enpl-1 (62% identical), Drosophila melanogaster Gp93 (60% identical). Paralogues in human: HSP90AB1 (45% identical), HSP90AA1 (44% identical), TRAP1 (27% identical).
Diseases named in the same sentence as HSP90B1 in open-access papers:
HSP90B1 is named in the same sentence as 229 diseases in open-access papers, as found by Europe PMC text mining. Sharing a sentence is not in itself a finding about the gene and the disease. The quoted sentences say what the papers report.
breast carcinoma (57 papers, 2007 to 2026). "High expression levels of endoplasmic reticulum resident HSP90B1 were shown to be associated with breast cancer metastasis and cancer cell migration." (PMID 29137250, 2017). "HSP90B1 overexpression has been associated with metastasis of breast cancer." (PMID 32153556, 2020). "It has been shown that HSP90B1 is regulated by Mir-99a-3p to participate in the pathogenesis of head-neck cancer, and the highly expressed HSP90B1 represents the poor prognosis of many tumors, including breast cancer and lung cancer." (PMID 36923505, 2023). "Highly expressed HSP90AB1 and HSP90B1 negatively correlated with the infiltration of CD4+ T cells in a study exploring immune infiltration in breast cancer." (PMID 38259468, 2023). "HSP90B1 mRNA expression has been reported to be elevated in several different cancer tissue types, including breast cancer, oesophageal cancer, glioma tissues, and liver cancer." (PMID 36291587, 2022). "For example, patients with breast cancer expressing high levels of HSP90B1 had a significantly lower survival time than those expressing low levels of HSP90B1." (PMID 36291587, 2022). "Following this, we performed an analysis of HSP90B1 protein expression in breast cancer, colon cancer, ovarian cancer, lung adenocarcinoma, clear cell RCC, and UCEC using the CPTAC dataset." (PMID 36291587, 2022). "Accordingly, the phosphorylation sites of HSP90B1 were significantly increased in breast cancer, LUAD, and clear cell RCC but significantly reduced in colon cancer." (PMID 36291587, 2022). "Dejean and Liu showed that the expression level of HSP90B1 in recurrent human breast cancer was higher than that of its matched primary tumor." (PMID 34109171, 2021). "Enhancing DC2 stimulatory potential by genetic deletion of Hsp90b1 (encoding molecular chaperon GP96) led to a similar enhancement of T cell immunity and improved survival in a spontaneous breast cancer model." (PMID 34283809, 2021). "It has also been reported that HSP90B1 helps cells to escape apoptosis and influence the function of various proto-oncogenes that are essential for breast cancer growth." (PMID 32537125, 2020). "HSP90B1 also helps cells escape apoptosis and preserves the function of various proto-oncogenes important for breast cancer growth." (PMID 22363530, 2012). "Both CNPY3 and HSP90B1 were overexpressed in breast cancers." (PMID 41296387, 2025). "Inhibition of HSP90B1 expression enhances chemotherapy in breast cancer studies." (PMID 40831924, 2025). "A recent study also shows that HSP90B1 plays a greater role in the carcinogenesis of breast cancer." (PMID 38711062, 2024). "Moreover, HSP90B1 also interacts specifically with HER2 on the cytoplasmic membrane of human breast cancers." (PMID 36291587, 2022). "In addition, HSP90B1 overexpression promoted the proliferation, migration, and invasion of bladder and breast cancer cells in vitro." (PMID 36452480, 2022). "Furthermore, Hsp90B1 is expressed in various types of cancer cells including breast cancer, human osteosarcoma, CML and non-small cell lung cancer." (PMID 27917123, 2016). "Additionally, the mutation of HSP90B1 showed an important effect on the progression-free survival of patients with BLCA patients and the overall survival and relapse-free survival of patients with breast cancer." (PMID 36291587, 2022). "Following the MS results the expression levels of DCN and HSP90B1 and their association with clinicopathological characteristics were further assessed in breast cancer tissues from an independent cohort compiled by the NCI and distributed as breast cancer prognostic TMAs." (PMID 22363530, 2012). "In a large group of breast cancer patients (n = 1907), patients with high levels of CNPY3 and HSP90B1 expression had shorten overall survival and progression-free survival." (PMID 41296387, 2025).
breast carcinoma (continued). "HSP90B1, a recognized tumor facilitator in several cancers such as NSCLC, bladder cancer, and breast cancer, presents an intriguingly high expression in NPC, the implications of which are yet to be fully understood." (PMID 38711062, 2024). "This compound results in the activation of ElF2A, HSP90B1/GRP94, HSPA5 and DDIT3 in HepG2 hepatoma and breast carcinoma MCF-7 cells." (PMID 36497321, 2022). "By determining the amount of total protein and phosphorylated protein, the probable molecular pathways of HSP90B1 in UCEC, breast cancer, blear cell RCC, Colon cancer, LUAD, and ovarian cancer can be elucidated." (PMID 36291587, 2022). "Utilizing the CPTAC database, researchers compared the phosphorylation levels of HSP90B1 in normal and primary tumour tissues of patients with UCEC, breast cancer, clear cell RCC, colon cancer, LUAD, and ovarian cancer, revealing significant differences." (PMID 36291587, 2022). "In summary, our results indicated that although gene expression levels of HSP90AA1, HSP90AA2, HSP90AB1, HSP90B1, and TRAP1 were upregulated in breast cancer patients, only the expression of HSP90AA1 was related to the tumor stage and prognostic survival." (PMID 34109171, 2021). "In this study, we investigated the expression patterns and prognostic values of different HSP90 family members (HSP90AA1, HSP90AA2, HSP90AB1, HSP90B1, and TRAP1) in breast cancer." (PMID 34109171, 2021). "Although the mRNA levels of HSP90AB1, HSP90B1, and TRAP1 were increased in breast cancer tissues compared with those in normal tissues, the mRNA levels were not significant." (PMID 34109171, 2021). "It is worth noting that HSP90B1, as a tumor-promoting factor, is highly expressed in non-small cell lung cancer, bladder cancer, and breast cancer, which is of great significance for patients’ prognosis." (PMID 38711062, 2024). "Other HSP90 isoforms, such as HSP90B1 and TRAP1, may affect treatment responses in specific subtypes of breast cancer and this effect could be largely diluted in the analysis of a heterologous population." (PMID 22510516, 2012). "Furthermore, we hypothesised a possible connection between genetic alterations in HSP90B1 and the clinical survival outcomes of UCEC, BLCA, and breast cancer." (PMID 36291587, 2022). "Five fusions (XPA-NCBP1, HARS2-ZMAT2, HSP90B1-DKFZp547P055, IL17RB-ACTR8, ANKRD23-ANKRD39) are identified to share with the fusions identified in prostate cancer but no fusions are shared with breast cancer, colorectal cancer, ovarian cancer, and lung cancer." (PMID 23251452, 2012).
melanoma (23 papers, 2011 to 2025). A malignant, usually aggressive tumor composed of atypical, neoplastic melanocytes. "SNX-2112, a selective Hsp90 (encoded by HSP90B1) inhibitors, has been reported to have potential antitumor effects in preclinical studies, including melanoma." (PMID 30779739, 2019). "A core group of differentially expressed genes (FTH1, FTL, HSPA8, HSP90AA1, and HSP90B1) was recurrently identified within significantly enriched pathways across TCGA melanoma samples and clinical cohorts." (PMID 32296058, 2020). "Activation of the signalling pathways associated with acute phase response, granzyme B, IL15, the upstream modulator, HSP90B1 and inhibition of the upstream modulator EOMES also indicated immune related mechanisms in development of melanoma metastasis." (PMID 33142795, 2020).
hepatocellular carcinoma (21 papers, 2010 to 2025). A malignant tumor that arises from hepatocytes. "HSP90B1 is proposed to be associated with poor survival from hepatocellular carcinoma (HCC), whereas high levels of HSPA5 and HSPA6 may be associated with earlier recurrence of HCC." (PMID 31101113, 2019).
lung carcinoma (21 papers, 2007 to 2025). "It has been shown that HSP90B1 overexpression is associated with an increased malignancy in a variety of cancers, including esophageal, colorectal, breast and lung cancers." (PMID 37750323, 2023). "Increased HSP90B1 expression has been shown to be an indicator of poor prognosis in patients with lung cancer, chronic lymphocytic leukemia, bladder cancer, and liver cancer." (PMID 35610596, 2022). "The primary disease related to GRP94/GP96 is lung cancer; in NSLC, overexpression of HSP90B1 is associated with poor prognosis; for adenocarcinoma, increased levels of GRP94/GP96 is associated with progression." (PMID 34449539, 2021). "Representatively, HSP90B1 was upregulated in lung cancer tissue compared with normal lung tissue in the Landi (P < 0.0001), Hou (P < 0.001), and Selamat datasets (P < 0.001)." (PMID 31970893, 2020). "We next examined whether HSP90B1 expression in lung cancer cells has any clinical significance by analyzing the raw data from the Oncomine Premium Edition upgrade." (PMID 31970893, 2020). "We first investigated HSP90B1 expression in human lung cancer." (PMID 31970893, 2020). "To further validate our RNA-Seq results, we utilized a different human lung cancer cell line H1838 and examined the expression level of COL1A2, LRP1, and HSP90B1, three representative genes up-regulated in our RNA-Seq analysis." (PMID 37487081, 2023). "Through q-RT-PCR analysis, we found six genes (DDR1, HSP90B1, SDC1, RPSA, ERGIC3, and LPCAT1) significantly up-regulated and two genes (GPX3 and TIMP3) significantly down-regulated in the lung cancer tissues." (PMID 23374247, 2013).
glioma (17 papers, 2009 to 2025). A benign or malignant brain and spinal cord tumor that arises from glial cells (astrocytes, oligodendrocytes, ependymal cells). "In gliomas, the HSP90B1 overexpression was also associated with the increased tumor aggressiveness and the worsening of clinical outcomes, implying a role for HSP90B1 in the development of GBMs." (PMID 37750323, 2023). "Accordingly, the transcript levels of HSP90B1 (the gene encoding the gp96 protein) were significantly higher in grade IV gliomas than in grade II/III gliomas." (PMID 35794988, 2022). "This heightened expression may suggest a significant association between the druggable protein HSP90B1 and glioma development, highlighting its importance as a potential therapeutic target for further investigation in glioma treatment strategies." (PMID 38665430, 2024). "Overall, our research revealed that HSP90B1 significantly impacts the prognosis of glioma patients treated with radiotherapy." (PMID 41716636, 2025). "A mouse model further demonstrated that gliomas expressing high levels of HSP90B1 exhibited decreased sensitivity to radiotherapy." (PMID 41716636, 2025). "Subsequent investigations revealed that HSP90B1 enhanced the proliferation, migration, and invasion of glioma cells." (PMID 41716636, 2025). "Among the genes involved in establishing IGF1RS, we observed that the exploration of HSP90B1 in gliomas was relatively limited." (PMID 38665430, 2024). "The HPA database was used to confirm the cytoplasmic localization of HSP90B1 in U251 human glioma cell lines by immunofluorescence." (PMID 38665430, 2024). "Immunohistochemical analysis confirmed that HSP90B1 was overexpressed in glioma, with significantly higher levels observed in glioblastoma than in astrocytoma or oligodendrocytoma." (PMID 38665430, 2024). "Using staining analysis of tissue from 101 glioma patients, the HSP90B1 protein was found to be significantly higher in tumor sections in GBM patients than in astrocytoma or oligodendrocytoma patients." (PMID 38665430, 2024). "In line with this, by exploring the glioma public database, we observed that HSP90B1 was most highly expressed in the most malignant mesenchymal subtype gliomas, and that patients with higher HSP90B1 expression had a poorer prognosis." (PMID 37750323, 2023). "As a member of HSP90 heat shock protein family whose expression is upregulated in various cancers, the downregulation of HSP90B1 revealed the consistency of these four manipulations on glioma suppression." (PMID 25007077, 2014). "Rescue experiments indicated that HSP90B1 might facilitate glioma migration, invasion, and radiotherapy resistance by modulating RhoC expression." (PMID 41716636, 2025). "Among them, few relevant studies have been conducted on HSP90B1 in glioma." (PMID 38665430, 2024). "Immunohistochemistry was used to evaluate the HSP90B1 level in clinical glioma tissue." (PMID 38665430, 2024). "In addition, the role and function of HSP90B1 as a prognostic biomarker in glioma should be further investigated using 3D cell culture and cell- or patient-derived xenograft models." (PMID 38665430, 2024). "In addition, HSP90B1 expression levels were significantly higher in GBMs (WHO grade IV) than those in gliomas of lower grades (including grades II and III), which has been suggested to be benefited from IR-based therapies (available online)." (PMID 37750323, 2023). "Additionally, HSP90B1 might enhance glioma metastasis and resistance to radiotherapy by regulating RhoC expression." (PMID 41716636, 2025). "Initial analyses of glioma patients from the Cancer Genome Atlas (TCGA) and the Chinese Glioma Genome Atlas (CGGA) databases who had undergone radiotherapy identified HSP90B1 as a crucial gene affecting patient prognosis." (PMID 41716636, 2025). "Moreover, the marker heat shock protein 90β family member 1 (HSP90B1) was screened from the genes included in IGF1RS and its expression was verified in cell lines and clinical glioma specimens." (PMID 38665430, 2024).
glioma (continued). "HSP90B1 expression did not segregate glioma patients on survival benefits when they did not receive IR treatment (left)." (PMID 37750323, 2023). "In vivo: Intracranial injection of U87, U87-RR (radioresistant U87 cells), and U87-RR/shHSP90B1 (HSP90B1-knockdown U87-RR cells) expressing luciferase.In vitro: Three GBM cell lines, namely U251, U87, and LN18, along with human embryonic kidney 293T cells and glioma stem cells (GSCs) MGG8." (PMID 39877360, 2024).
myeloma (17 papers, 2010 to 2025). "Furthermore, the dual inhibition of HSP90 A and HSP90B1 by PU-H71 emerges as a potential breakthrough in myeloma treatment." (PMID 39564119, 2024). "Furthermore, the dual inhibition of HSP90A and HSP90B1 by PU-H71 proves highly effective in the context of myeloma, providing fresh hope for patients with this challenging malignancy." (PMID 39564119, 2024). "The HSP90B1 (endoplasmin) gene encodes a heat shock chaperone, which was reported to interfere with TGF-β signaling, and is associated with the progression of multiple myeloma, breast cancer and osteosarcoma, to mention a few examples." (PMID 36232621, 2022).
gastric cancer (16 papers, 2007 to 2025). A primary or metastatic malignant neoplasm involving the stomach. "In gastric cancer cells, HSP90b1 interacts with the client protein LRP5 and inhibits the ubiquitin–proteasome degradation pathway of LRP5, thereby influencing the progression of gastric cancer." (PMID 39048939, 2024).